IL18 (interleukin 18)
Diseases named in the same sentence as IL18 in open-access papers (continued):
Sharing a sentence is not in itself a finding about the gene and the disease.
Stroke (continued). "As important cytokines in vivo, IL1β, and IL18 play important roles in the progression and prognosis of many neurological diseases, including stroke and glioma." (PMID 38405399, 2024). "IL-18, a novel biomarker for PSD, is independently associated with depressive symptoms after stroke." (PMID 38421829, 2024). "After a stroke, mitochondria govern the NLRP3 inflammasome by discharging molecular contents, which release pro-inflammatory cytokines such as IL-1β and IL-18, driving the inflammatory response, potentially linked to post-stroke depressive-like behaviors." (PMID 38377025, 2024). "Exercise preconditioning inhibited the protein expression of NLRP3, Caspase-1, IL-18, and IL-1β to improve cognitive dysfunction in stroke mice." (PMID 38317957, 2024). "Early RIC remarkably ameliorated the notable elevation of IL‐18 and IL‐1β levels after stroke as detected by ELISA (p < 0.05)." (PMID 37580991, 2023). "A151 treatment resulted in reduced expression of cGAS, AIM2, IL-1β and IL-18 after experimental stroke and decreased infarct volume and improved neurological deficits after stroke." (PMID 37212886, 2023). "IL 1β and IL-18 were increased in stroke (p<0.001 stroke vs. steady state), while IL-33 was decreased (p<0.05 stroke vs. steady state)." (PMID 36969226, 2023). "Ritonavir, once a protease inhibitor used to treat HIV, was later found to effectively reduce the level of IL-18 in mouse pancreatic cancer by suppressing caspase-1 activation with the potential application in stroke." (PMID 35370546, 2022). "Increased IL-18 and IL-8 expressions contributed to the development and severity of stroke and IL-18 also participated in hypoxic-ischemic brain injury." (PMID 36439158, 2022). "Conclusively, we showed that the receptors of NLRP3, NLRC4, and AIM2, the executors of Caspase-1 and−11 were the main contributors of-post stroke inflammasome activation, which participated in the production of IL-1β, IL-18, and GSDMD." (PMID 33967935, 2021). "Microglial pyroptosis can promote the release of intracellular IL-1β and IL-18, contributing to proinflammatory responses after stroke." (PMID 34630845, 2021). "The studies found that the levels of NLRP3 inflammasome proteins, IL-1β and IL-18 were elevated in stroke patients, and also increased in ipsilateral brain tissues of MCAO C57BL/6J mice and primary cortical neurons exposed to OGD." (PMID 32153398, 2020). "The results demonstrated that proinflammatory cytokines TNF-α (p < 0.05), IL-6 (p < 0.001), IL-1β (p < 0.01), IL-17 (p < 0.01), and IL-18 (p < 0.01) were increased in wild-type mice subjected to stroke." (PMID 32450881, 2020). "We found in the cross-sectional study that IL-18 level in stroke patients was higher than those in controls." (PMID 31525735, 2019). "A subsequent meta-analysis confirmed that IL-18 level was higher in stroke patients than in controls (SMD = 2.14, 95% CI = 1.54 ∼ 2.73, P< 0.001)." (PMID 31525735, 2019). "We found IL-18 was higher in stroke patients than in controls (2.39 ± 0.25 vs. 2.25 ± 0.28, F=8.60, p=0.004) and was negatively associated with the NIHSS scale (r = -0.14, p=0.028)." (PMID 31525735, 2019). "We have previously shown that the inflammasome, an arm of the innate immune response involved in the activation of caspase-1 and the pro-inflammatory cytokines interleukin (IL)-1β and IL-18, contributes to the pathology of stroke." (PMID 30233311, 2018). "IL-18 is also present in the area of liquefactive necrosis for at least eight weeks following stroke, and there are also strikingly high levels of MMP-2, MMP-3, and MMP-8." (PMID 30417081, 2018). "Protein levels of caspase-1, ASC and IL-18 were higher in the serum of stroke patients when compared to the control samples, whereas levels of IL-1β were not significantly different." (PMID 30233311, 2018).
Stroke (continued). "Accordingly, we found evidence of NLRP3 inflammasome activity within ischemic stroke infarcts during the chronic stage of liquefactive necrosis by way of a significant elevation of IL-18 at four and eight weeks following stroke." (PMID 30417081, 2018). "Lower levels of IL-18 by NaB at both 2 and 5 days post stroke is particularly interesting in view of the data that this cytokine is reported to have prognostic value in patients with acute ischemic stroke." (PMID 27905989, 2016). "Our data show that NaB decreased pro-inflammatory cytokine levels of IL-1beta in circulation at 2 days post stroke and both IL-18 and IL-1beta at 5 days post stroke." (PMID 27905989, 2016). "These clinical reports are consistent with our observation in middle-aged female rats where higher IL-18 levels in the saline-treated group is accompanied by worse sensory motor function as compared to the post-stroke NaB-treated group." (PMID 27905989, 2016). "Another pro-inflammatory cytokine, IL-18, was also decreased in post-stroke NaB-treated group (166.2 ± 20.34 pg/ml) as compared to the levels in post-stroke saline-treated group (249.1 ± 25.49 pg/ml) at 5 days (p = 0.0366)." (PMID 27905989, 2016). "In the ischemic hemisphere, NaB decreased IL-18 at 2 days post stroke and IL-1beta, IL-17a, and IL-18 at 5 days post stroke." (PMID 27905989, 2016). "Zaremba and colleagues have shown that serum IL-18 level is significantly elevated in stroke patients as compared to controls, and IL-18 levels were negatively correlated with both the Scandinavian Stroke Score and the Barthel Index." (PMID 27905989, 2016). "Previous study has shown that genetic polymorphisms of IL-18 -607A/C and -137C/G in the promoter IL-18 gene may affect the immune response, and can have a role in the risk of several kinds of diseases, such as tuberculosis, cancers, coronary artery disease and stroke." (PMID 25878643, 2015). "IL-18 expression was detectable at low levels within the first days and peaked at 7 days after stroke." (PMID 21171972, 2010). "Recently, IL-18 expression and activation has been described already at 24 hours in a thromboembolic murine stroke model." (PMID 20150990, 2010). "In addition, JDHXD has an important protective effect on the prognosis of stroke by inhibiting IL-1β and IL-18 produced downstream of pyroptosis." (PMID 39139639, 2024). "IL-18 is associated with stroke-induced inflammation and that initial serum IL-18 levels may be predictive of stroke outcome." (PMID 35173738, 2022). "Although IL-18 was shown to mediate inflammatory response resulting in loss of appetite, sleep dysregulation, and several neurodegenerative diseases, caspase-1 mediated IL-18 on BBB in stroke deserves further exploration." (PMID 35370546, 2022). "Authors concluded that IL-18 is predictive of PSD in the first 2 weeks after stroke." (PMID 33919670, 2021). "Limited to cross-sectional relationships, it does not firmly establish that IL-18-mediated inflammation is associated with cognitive decline nor with other conditions associated cSVD indicators, namely the risk of stroke and/or dementia." (PMID 31978079, 2020). "A decrease in brain IL-15 and IL-18 levels at day 10 along with reduced gliosis at day 30-post stroke could partially explain the protective role of GDF11." (PMID 32365331, 2020). "IL-18 level markedly increased in stroke and were positively related to the severity of stroke." (PMID 31525735, 2019). "IL-18 level increased with the severity of the stroke (p< 0.01)." (PMID 31525735, 2019). "In conclusion, our present study provides evidence for the involvement of IL-18 in stroke." (PMID 31525735, 2019). "NLRP3 inflammasome activation following stroke is established in earlier studies to contribute to stroke injury through the pro-inflammatory cytokines (e.g. IL-1, IL-18) as well as the pleiotropic effects of cleaved caspase-1 in mediating pyroptosis and apoptosis." (PMID 29654318, 2018).
Stroke (continued). "IL-18 is also induced during physical/emotional stress responses and high levels of IL-18 are detected in several neuropathological conditions such as during microbial infections, following trauma, stroke, or ischemia." (PMID 26728085, 2016). "IL-18 is involved in stroke-induced inflammation and that initial serum IL-18 levels may be predictive of stroke outcome." (PMID 27679860, 2016). "Along this line of evidence, IL-18 after stroke is produced by microglia and contributes to fibrosis in the aged rat brain via STAT3 activation, leading to a large accumulation (237-fold over controls) of collagen III (Col3a1) transcripts that are normally expressed in adventitial fibroblasts." (PMID 24672479, 2014). "IL18 is a reliable predictor of worse outcome in stroke and myocardial infarction." (PMID 23874624, 2013). "Coincidentally, IL-18 is also elevated after stroke, a condition followed by emotional disorders." (PMID 20113500, 2010). "Additionally, the role of the AIM2 inflammasome was examined in stroke-induced cognitive impairment in elderly mice, which demonstrated that AIM2 mRNA and protein, combined with caspase-1, IL-1β, and IL-18, were enhanced in the hippocampus and cortex after stroke." (PMID 37450925, 2023). "A number of publications have reported different inflammasomes activation implicated in stroke, such as NLRP1, NLRP3, and AIM2, which contribute to activation of Caspase1 that shears the precursors of IL-1β and IL-18 into their mature forms (cl.IL-1β and cl.IL-18)." (PMID 35690810, 2022). "IL-18 level might be considered a potential biomarker for stroke." (PMID 31525735, 2019). "In line with previous studies of the etiology of ischemic stroke, some researchers have proposed the hypothesis that a pro-inflammatory profile induced by increased IL-18 level creates a pro-thrombotic and pro-atherosclerotic environment, which may eventually contribute to stroke in older people." (PMID 31525735, 2019). "However, two recent nested case-control studies have not confirmed an association of IL-18 with increased risk of stroke in older people or with recurrent stroke." (PMID 20150990, 2010). "We found that IL-18, MMP-9, DMTS, DWMH, brain atrophy, previous stroke, hypertension, and female sex were directly and positively correlated with PSCI." (PMID 40821836, 2025). "In the present study, we demonstrated that THSWD attenuated mitochondrial DNA and nuclear DNA damage during stroke; reduced AIM2, NLRC4, and Caspase-1 inflammasomes; and inhibited IL-1β and IL-18 inflammatory factor release after IS." (PMID 36034843, 2022). "Post-stroke inflammasome activation, especially NLRP3, cleaved Caspase-1, cleaved Caspase-11, IL-1β, IL-18, and GSDMD, peaked at 3–5 days and declined at 7 days with the participation of multiple components in mice." (PMID 33967935, 2021). "To verify the anti-inflammatory function of Gen after reproductively senescent stroke, we evaluated inflammatory factors, including TNF-α, IL-1β, IL-18, and IL-6 in ischemic penumbra area 24 h after reperfusion." (PMID 32625078, 2020). "We then isolated EV from the serum of 16 aged-matched donors and 16 stroke samples and analyzed the protein levels of caspase-1, ASC, IL-1β, and IL-18 in these isolated EV with the Simple Plex technology." (PMID 30233311, 2018). "Stroke induces the release of pro-inflammatory cytokines, such as interleukin-6 (IL-6), interleukin-1β (IL-1β), tumor necrosis factor-α (TNF-α), and interleukin-18 (IL-18), while reducing anti-inflammatory cytokines like IL-10 and IL-13." (PMID 40529498, 2025). "Higher levels of IL-6 and IL-18 are related to PSD at 2 weeks and 1 year after stroke." (PMID 40529498, 2025). "However, the effects NLRP3 inflammasome activation and pyroptosis after stroke were attenuated by IPC, which decreased the expression of NLRP3, ASC, cleaved caspase 1, and GSDMD-N and reduced the production of IL-1β and IL-18." (PMID 37371374, 2023).
Stroke (continued). "For subtypes of stroke, IS and ICH, higher levels of growth regulated oncogene-α, beta nerve growth factor, IL-18, macrophage colony-stimulating factor, and induced protein 10 upregulated the risk factors while lower levels of IL-2ra and IL-17 upregulated the risk factors." (PMID 38089678, 2023). "This was corroborated by literature publishing that TNF-α, IL-1B, IL-6 and IL-18 also independently predicted the occurrence of PSD in the acute to subacute period, and elevated IL-6, IL-10 and TNF-α correlates with PSD at one to three months post stroke." (PMID 33919670, 2021). "Second, we did not classify stroke subtypes to examine the IL-18 level among these different subgroups." (PMID 31525735, 2019). "Concerning the limitations of our study, our findings are constricted by the lack of longitudinal assessments of IL-18 level in larger stroke cohorts together with clinical findings, especially regarding the specific location of lesions." (PMID 31525735, 2019). "However, our study suggested a negative correlation between the severity of DWMH at stroke onset and IL-18 levels." (PMID 40821836, 2025). "In summary, our findings in adult IL-18 knock-out mice support the notion that IL-18 is not functionally relevant for early stroke development, but may play a role in late-stage neuroinflammation after stroke which awaits further elucidation." (PMID 20150990, 2010). "Although this study found that the improvement of stroke by acupuncture was related to the upregulation of SIRT1 expression levels in brain tissue and the significant downregulation of the expression levels of NLRP3 and IL-18, the specific in-depth mechanisms were not further studied." (PMID 36059399, 2022).
Arthritis (65 papers, 2006 to 2026). Inflammation of a joint. "In contrast to these results, we did not observe any significant differences regarding the severity of arthritis, including articular Csf2 mRNA levels, in IL-18-deficient as compared to WT mice." (PMID 37415987, 2023). "According to some recent reports, high serum levels of IL-18 in PsA are associated with arthritis and skin inflammation and with an increased level of IL-17, an interleukin playing a key role in the pathogenesis of axial of SpA." (PMID 35160217, 2022). "More recently, patients with PSTPIP1 mutations causing neutrophilic skin rashes and arthritis were found to have chronic elevation of IL-18." (PMID 36096831, 2022). "The level of IL-18 reportedly increased in both the serum and synovial fluid samples of RA patients, and IL-18-deficient mice were shown to have a reduced incidence and severity of arthritis in preclinical models." (PMID 33092271, 2020). "We have sought to determine the mechanisms underlying the activation of IL-18/IL-18Rα signaling in the immune system’s response to LPS-induced arthritis." (PMID 31861496, 2019). "IL-18 administration resulted in higher arthritis incidence and severity, while IL-18-deficient mice showed reduced arthritis incidence and severity." (PMID 22537858, 2012). "The present study also shows that haplotype S01 of the IL18 gene is widely linked to susceptibility to arthritis in the Japanese population." (PMID 16563174, 2006). "As compared to WT mice, IL-18-deficient mice showed a reduced incidence and severity of arthritis associated with decreased spleen and lymph node cell proliferation and pro-inflammatory cytokine production in response to ex vivo stimulation with bovine type 2 collagen." (PMID 37415987, 2023). "In addition, IL-18 gene polymorphisms were found to be significantly associated with the occurrence of arthritis symptoms in SLE patients." (PMID 30202244, 2018). "The 1,407 genes with increased expression in DA and reciprocally decreased expression in DA.F344(Cia5a) congenics included pro-inflammatory cytokines and chemokines implicated in arthritis pathogenesis such as Il1b (5.17-fold on microarray, and 2.46-fold on qPCR), Il18, Mif, Ccl2, Ccl7 and Cxcl13." (PMID 23249408, 2012). "This study examines the expression and function of IL-18 and IL-18BP in K/BxN serum transfer arthritis (STA), a model that is uniquely dependent on innate immune responses." (PMID 37415987, 2023). "Using the K/BxN STA model, IL-18 was recently shown to contribute to the severity of arthritis and intra-articular neutrophil recruitment via the stimulation of synovial NK cells to produce GM-CSF." (PMID 37415987, 2023). "To further assess the severity of arthritis, we measured the mRNA levels of a variety of pro-inflammatory cytokines and chemokines, including Il18bp, Il18, Il1b, Il6, Il1r2, Ifng, Cxcl9, Cxcl1, and Cxcl2 in arthritic joints of IL-18BP KO and WT littermates." (PMID 37415987, 2023). "The incidence and severity of arthritis, including mRNA levels of different cytokines, were compared in IL-18BP or IL-18 knock-out (KO) mice and their WT littermates." (PMID 37415987, 2023). "Naïve and serum transfer-induced arthritis (STA) wild-type (WT) mice were used to examine the articular levels of IL-18 and IL-18BP mRNA by RT-qPCR." (PMID 37415987, 2023). "The incidence and severity of arthritis were similar in IL-18BP KO and IL-18 KO compared to their WT littermates." (PMID 37415987, 2023). "Since both sJIA and AOSD are characterized by dysregulated innate immune responses, we decided to investigate the role of the IL-18/IL-18BP balance in an experimental model of arthritis that is uniquely dependent on innate immune responses." (PMID 37415987, 2023). "Along with strikingly high levels of IL-18, arthritis is another key clinical manifestation of AOSD and sJIA." (PMID 37415987, 2023).